INS (insulin)
Diseases named in the same sentence as INS in open-access papers (continued):
Sharing a sentence is not in itself a finding about the gene and the disease.
Hypoglycemia (continued). "Furthermore, we hypothesized that the use of fixed insulin regimens and excessive latency in adjusting insulin doses to seasonal variations and heat waves exposed patients to a risk of deterioration in glycemic control, including a higher incidence of hypoglycemia." (PMID 41464483, 2025). "Furthermore, children and adolescents, as well as their parents, were found to become upset with alerts, overtreating hypoglycemia with carbohydrates, even in the case of sensor-augmented insulin pumps." (PMID 41462808, 2025). "In the results of the univariate analysis, we also found that whether insulin was used during the operation was a significant factor in the occurrence of hypoglycemia." (PMID 40692592, 2025). "Furthermore, insulin therapy is limited by hypoglycemia and weight gain, forcing some to reduce their insulin dose, leading to poor glycemic control." (PMID 40852189, 2025). "Their excessive insulin secretion can lead to significant clinical manifestations, typically characterized by Whipple’s triad, indicated by symptoms of neuroglycopenia occurring during episodes of hypoglycemia, which resolve with glucose correction." (PMID 39968426, 2025). "The degree of C-peptide, insulin elevation, in the correct clinical setting of the acute hypoglycemia may serve as a clue to tramadol-induced hypoglycemia." (PMID 40083398, 2025). "Additionally, once‐weekly insulin showed increased rates of level 1 and level 2 nocturnal hypoglycemia." (PMID 40186384, 2025). "Peripheral injection of FGF1 in diabetic HFD-fed mice and ob/ob mice restored normoglycemia, improved insulin sensitivity, reduced hepatic steatosis and inflammation, independent of weight loss, and without inducing hypoglycemia." (PMID 41072794, 2025). "However, it has been recently announced that Medicare will once again expand its coverage of CGMs to any person on insulin therapy and/or history of hypoglycemia." (PMID 40278537, 2025). "The safety profile is similar to that of other GLP-1 RAs, with mild-to-moderate gastrointestinal side effects being the most common and a low risk of hypoglycemia, especially in patients not using insulin or sulfonylureas." (PMID 39917155, 2025). "However, the role of increased insulin sensitivity in hypoglycemia is less likely in acute states, as these are typically characterized by elevated levels of counterregulatory hormones and proinflammatory cytokines." (PMID 40150028, 2025). "Patients with hypoglycemia often suffer from symptoms such as dizziness, nausea, physical fatigue, and this is in most cases due to the overdose of oral antidiabetics and injection of insulin therapy." (PMID 41393767, 2025). "Despite mild hypoglycemia due to very rapid weight loss and improved insulin sensitivity with concomitant insulin therapy, no further adverse events occurred in this case." (PMID 40302276, 2025). "Remarkably, treating the lean RCD group with shChREBP does not cause hypoglycemia nor does it alter glucose tolerance and insulin sensitivity." (PMID 40311678, 2025). "The ACTH-cortisol axis showed a lack of responsiveness in both the corticotropin-releasing hormone (CRH) and insulin-induced hypoglycemia tests, but responded to the continuous ACTH infusion, indicating adrenal cortex functionality but deficient endogenous ACTH secretion." (PMID 40677481, 2025). "In addition, the profound depletion of glycogen stores in infected GRiKO and adrenalectomized mice, as well as reduced glycogen presence in post-mortem liver sections from malaria patients, further supports the notion of insulin-independent hypoglycemia." (PMID 40702267, 2025). "The VRIII needs meticulous 1–2 hourly measurements of the capillary glucose, and subsequent adjustments to the rate of the insulin infusion, otherwise dangerous hypoglycaemia may result." (PMID 40480914, 2025).
Hypoglycemia (continued). "However, tests to investigate the condition revealed a high insulin dosage in the presence of hypoglycemia, and the patient was referred to a pediatric endocrinologist." (PMID 40136120, 2025). "Insulin therapy may accelerate this process, particularly in situations characterized by significant glycemic fluctuations and frequent episodes of hypoglycemia." (PMID 40997126, 2025). "While younger age and males were associated with higher hypoglycemia rates, these factors were not significant predictors in the regression analysis, suggesting that other factors, particularly insulin use, play a more critical role in hypoglycemia risk." (PMID 41393767, 2025). "This dual hormone response is crucial and acts in concert to ensure that blood glucose levels remain stable, preventing hypoglycemia that might occur from a sudden insulin spike." (PMID 40647197, 2025). "Therefore, a clearer understanding of the pathological and molecular basis is essential not only for more accurate forensic diagnosis but also for guiding the management of severe hypoglycemia in insulin-treated patients." (PMID 41303503, 2025). "Patients may present with fatigue, dizziness, sweating, and flushing attributed to hypoglycemia, after large amounts of insulin are secreted in response to high circulating glucose concentration." (PMID 40427747, 2025). "Insulinomas are rare insulin-secreting pancreatic neuroendocrine tumors (PNETs) that can cause profound hypoglycemia, particularly in non-diabetic patients." (PMID 40757084, 2025). "In addition, the average individual on insulin therapy will typically experience symptomatic hypoglycaemia 2–3 times per week." (PMID 40227271, 2025). "In primary prevention, the behaviour (e.g., insulin omission with the intention to control weight, or significant food restriction leading to problematic hypoglycaemia or weight loss) has not (in theory) manifested yet." (PMID 39902232, 2025). "Treatment of hypoglycemia associated with NIPHS involves nutritional modification consisting of mixed meals high in protein and low in carbohydrates to assist with reduction in postprandial insulin secretion." (PMID 40648766, 2025). "Instead, the study found that insulin use was a significant predictor of hypoglycemia." (PMID 41393767, 2025). "Under hyperglycemic conditions, it amplifies the insulin response without increasing the risk of hypoglycemia, a common and serious concern with many traditional antidiabetic therapies." (PMID 41405657, 2025). "Additionally, the smaller decrease in HbA1c in patients with T1D compared to patients with T2D after the addition of a GLP-1RA has been attributed to a concomitant decrease in prandial insulin dose to avoid post-prandial hypoglycemia." (PMID 40760325, 2025). "More specialist expertise is required to ensure safe insulin administration, such as in teaching patients about proper injection techniques, insulin storage, adjusting insulin doses, and recognising and managing hypoglycaemia." (PMID 40559086, 2025). "There was consensus in recommending capillary glucose monitoring during hospitalization, the use of basal and prandial insulin coverage, achieving target glucose levels between 100 and 180 mg/dL while preventing and treating hypoglycemia, and planning the patient’s transition to home care." (PMID 41464722, 2025). "Adding an SGLT2i at a lower than usual dose to insulin therapy in these patients may facilitate glucose control and decrease glucose excursions, thereby reducing insulin doses and hypoglycaemia." (PMID 40968746, 2025). "Congenital hyperinsulinism (CHI) is the most common cause of severe and persistent hypoglycemia in early childhood characterized by dysregulated insulin production by pancreatic β cells, resulting in excess insulin secretion independent of plasma glucose (PG)." (PMID 39584500, 2025).
Hypoglycemia (continued). "Whilst early trials showed improvement in postprandial glucose control in adolescents prone to missed insulin boluses, these systems remain vulnerable to unannounced meals and sensor error, often requiring refinement to prevent mistimed dosing or hypoglycaemia." (PMID 40718205, 2025). "Previous reports suggest that the sulfonamide structure of sulfamethoxazole induces adenosine triphosphate-sensitive potassium channels and insulin secretion in mice, which may explain the clinical hypoglycemia observed." (PMID 40725512, 2025). "A study in Southwest, Ethiopia and Turkey also explained that lack of knowledge on insulin self-administration was factor associated with high rate of reported hypoglycemia." (PMID 40110390, 2025). "Following delivery, when the glucose supply is ceased, the newborn is at risk of developing hypoglycemia due to the elevated insulin concentration that persists in the absence of glucose." (PMID 39796611, 2025). "Hypoglycosylation due to PMM2 deficiency could impair the function of the KATP complex leading to increased insulin secretion and hypoglycemia." (PMID 40771275, 2025). "These programs should emphasize practical and hands-on components such as injection site rotation, hypoglycemia management, insulin storage/mixing and needle reuse prevention to address specific knowledge deficits identified in the study (e.g., 47.7% poor knowledge rate)." (PMID 40900896, 2025). "This resulted in mild but recurrent hypoglycemia under insulin therapy." (PMID 40302276, 2025). "This growing popularity can be attributed to the advancements in pump technology, including features like automatic insulin suspension during hypoglycemia and the availability of tubeless pumps, as well as increased accessibility due to healthcare systems reimbursements." (PMID 41149081, 2025). "The patient denied alcohol consumption or intentional or accidental administration of medications that could induce hypoglycemia (insulin, sulfonylureas)." (PMID 39941267, 2025). "This considered, we can speculate that females may be more likely to suffer severe hypoglycemia after tumor removal, due to the recovery of insulin secretion after tumor surgery." (PMID 40589516, 2025). "This is an indication that insulin therapy is an effective treatment alternative for some patients, especially those who demand more rigorous management of their glycemic levels in case of discomfort during injection and hypoglycemia." (PMID 40959330, 2025). "In contrast, similar HbA1c values in insulin-treated KTA recipients may mask substantial hypoglycaemia burden, glycaemic fluctuations, and the cognitive and emotional load of intensive insulin management." (PMID 41536836, 2025). "Non-availability of insulin in resource-limited settings, lack of compliance, emergence of adverse effects, risk of hypoglycemia and the need for self-monitoring of blood sugar levels, restrict the usage of insulin in real-world settings." (PMID 40680017, 2025). "The dose of the meal‐time component of IDegAsp is limited by the dose of basal insulin, therefore, a higher ratio of iAsp to IDeg may lead to lower prandial excursions, perhaps at a cost of increased hypoglycaemia." (PMID 40176458, 2025). "We recently found that isolated male mice were refractory to insulin-induced hypoglycemia." (PMID 41509225, 2025). "In cases where exogenous insulin is implicated, significantly elevated plasma insulin levels and suppressed C-peptide levels during hypoglycemia confirm the absence of endogenous insulin secretion." (PMID 39030378, 2025). "Providers may have lowered insulin doses for CD+ individuals experiencing hypoglycemia, reducing insulin-glucose mismatch." (PMID 40990290, 2025). "The observed weight gain in this study where both groups received insulin titration is likely due to a combination of the anabolic effect insulin has in inhibiting protein breakdown and increased calorie intake by participants trying to prevent hypoglycemia." (PMID 41476921, 2025).
Hypoglycemia (continued). "Fourth, data on insulin‐on‐board were not available, which precludes assessment of its potential influence on hypoglycemia risk during and after PA." (PMID 40926369, 2025). "The inhibition of this receptor causes a diuretic effect causing the excretion of both sodium and glucose, presenting a non-insulin-dependent way of reducing serum glucose levels without increasing the risk of hypoglycaemia." (PMID 41516231, 2025). "This study also showed that increasing the glucose target at the onset of exercise or 45 min prior to the start of exercise was less effective for avoiding hypoglycaemia than setting a higher glucose target 90 min before exercise when prandial insulin was reduced by 25%." (PMID 39653802, 2025). "Its effect relies on renal and intestinal glucose excretion rather than insulin secretion, which reduces the risk of hypoglycemia, especially at lower glucose levels." (PMID 40529829, 2025). "When glycemic and blood pressure control is achieved, clinicians should consider de-escalation strategies, including dose reduction or discontinuation of other antihyperglycemic agents (e.g., insulin) and antihypertensives, to mitigate the risks of hypoglycemia and hypotension." (PMID 41404511, 2025). "Thus, continued health education of Patients living with T1D regarding insulin self-administration and awareness of hypoglycemia symptoms is necessary to prevent further complications." (PMID 40110390, 2025). "In insulin‐treated individuals, C‐peptide may help identify those more likely to experience hypoglycaemia or higher glycaemic fluctuations." (PMID 39797595, 2025). "Common adverse effects of insulin include hypoglycemia and weight gain." (PMID 40979703, 2025). "Impaired insulin secretion in the setting of malnutrition, although seemingly protective against hypoglycemia, may also lead to decreased glycogen replenishment, as insulin is a stimulus for glycogenesis." (PMID 40648766, 2025). "We hypothesized that the increased insulin sensitivity is the main driver of fasting hypoglycemia in GH insensitivity, limiting metabolic counter-regulatory mechanisms such as hypoglycemia-induced EGP promotion and lipolysis." (PMID 41125144, 2025). "Interestingly, participants with a BMI ≥25 kg/m2 experienced a reduction in daily insulin doses concurrently with a decrease of time spent in hypoglycemia." (PMID 41473236, 2025). "Since this insulin response lags and remains active longer than the elevated glucose levels, hypoglycemia may subsequently occur." (PMID 41133541, 2025). "However, combination treatments come with potential risks, such as an increased likelihood of hypoglycemia (mainly when insulin or sulfonylureas are used), higher medication costs, and difficulties with adherence due to complex regimens." (PMID 40507585, 2025). "In adults with T1D, nutrition around exercise must be carefully managed, considering individualized macronutrient needs, fluid intake, supplementation, and if necessary, insulin dosing adjustments to prevent hypoglycemia, optimize performance, and support recovery." (PMID 41141270, 2025). "Although insulin pump therapy can more accurately imitate the natural insulin release in the body, it can also provide more effective insulin delivery to tissues and reduce the likelihood of hypoglycemia episodes." (PMID 41146752, 2025). "Improper use of insulin can lead to hypoglycemia or low blood sugar." (PMID 40491970, 2025). "Moreover, this hypoglycemia/insulin-induced copeptin and glucagon elevation is notably attenuated in individuals with type 1 diabetes (T1D) compared to non-diabetic BMI and age-matched controls." (PMID 40428796, 2025). "Drug-induced hypoglycemia may occur in any type of diabetes, mainly as a side effect of treatment with insulin or sulfonylureas." (PMID 40893590, 2025). "Since it does not require multiple insulin doses like an artificial pancreas, the risk of hypoglycaemia is minimized." (PMID 40836936, 2025).
Hypoglycemia (continued). "Some clinicians may also adjust insulin levels to prevent hypoglycemia when adding on medications such as thiazolidinediones or glucagon-like peptide-1 receptor agonists (GLP-1 RAs)." (PMID 40156735, 2025). "T1D treatment is a challenge, since imperfect, exogenous insulin administration aims to mimic (inexistent) endogenous insulin production, to keep glucose concentrations within a safe range, avoiding hyper- and hypoglycemia (high and low blood glucose levels, respectively)." (PMID 40585404, 2025). "The use of GLP-1 receptor analogs markedly reduces the risk of hypoglycemia, because they do not induce insulin secretion when glucose concentrations are low." (PMID 39826690, 2025). "However, excessive insulin administration can induce hypoglycemia, characterized by dangerously low BGL, leading to immediate symptoms such as drowsiness, tremors, confusion, loss of consciousness, seizures, and in severe cases, coma or fatality." (PMID 39869550, 2025). "The CGMS improves the detection of hypoglycemic episodes and might decrease the frequency of clinical hypoglycemia when used for insulin dose titration." (PMID 40105400, 2025). "Depending on our comparison between URAIs and standard insulin, individualized treatment selection is crucial; Despite offering improved glycemic stability and reduced hypoglycemia, the cost appears to be an increase in infusion site reactions, necessitating careful risk-benefit assessment." (PMID 40547532, 2025). "Because it is a rare cause of hypoglycaemia, a thorough examination should be performed to rule out other causes of hypoglycaemia (infection, liver failure, exogenous insulin...)." (PMID 39931615, 2025). "Comorbidities like chronic kidney disease or liver dysfunction, which increase hypoglycaemia especially nocturnal by altering insulin metabolism and neoglucogenesis, may be better suited to morning Gla-300 administration to avoid hypoglycemia." (PMID 40190894, 2025). "In pregnancies complicated by T1DM, intensive insulin regimens via multiple daily injections, continuous subcutaneous insulin infusion, or hybrid closed-loop systems assist in reducing hypoglycemia and maintain stability of insulin requirements as they fluctuate throughout pregnancy." (PMID 41010783, 2025). "The BBT + E group demonstrated a narrower range of insulin dose adjustments without dose reduction, which potentially minimised the risk of hypoglycemia." (PMID 40828947, 2025). "The Soli‐D study demonstrated improved glycaemic control, body weight benefit, a greater proportion of participants at HbA1c target, lower total insulin dose and lower incidence and event rate of hypoglycaemia, albeit with an increased rate of gastrointestinal AEs." (PMID 40176458, 2025). "An advantage of this class of drugs is that they do not cause hypoglycemia unless they are used in combination with other agents (sulfonylureas, insulin, etc.)." (PMID 41012462, 2025). "Furthermore, for basal insulin regimen, it is generally recommended to maintain the dose and timing unless episodes of overnight hypoglycemia have occurred." (PMID 40432987, 2025). "As the regular human insulin (RHI) dose increases, there is not only an increase in insulin exposure and metabolic activity but also an increase in the duration of insulin action, which increases the risk of late postprandial hypoglycemia." (PMID 40574081, 2025). "In addition, when hypoglycemia was induced by insulin administration, it significantly diminished the neuronal activation elicited by female−soiled bedding, mainly in the nesfatin−1−positive neurons." (PMID 39859453, 2025). "The system should function as a stable in situ depot offering controllable insulin release without inducing hypoglycemia and gradually degrade without causing long-term toxicity or immunological rejection." (PMID 40292663, 2025).